POLE (DNA polymerase epsilon, catalytic subunit)
Diseases named in the same sentence as POLE in open-access papers (continued):
Sharing a sentence is not in itself a finding about the gene and the disease.
cancer (continued). "In addition to TMB‐high, the future is expected to establish missense mutations in the polymerase epsilon (POLE) gene as a biomarker for immunotherapy across various cancer types." (PMID 39315676, 2024). "Mechanisms and consequences of POLE mutations in human cancers." (PMID 37891003, 2024). "The fact that POLE mutations found in hypermutated tumors are located within highly conserved amino acid residues in the exonuclease domain strongly supports that loss of proofreading activity is responsible for the accumulation of mutations in these cancers." (PMID 37891003, 2024). "POLE mutations that impair DNA proofreading lead to increased mutagenesis, and in the germline confer an increased risk of colorectal, endometrial, and other cancers." (PMID 38282550, 2024). "Such exploration and knowledge for the minority of POLE-mutated cancers that escape immunotherapy might help for the orientation of alternative therapies of patients and implementation of surveillance to their family members." (PMID 37891003, 2024). "Recently, we have reported an exceptional cancer-related hereditary POLE mutation, N363K, which not only affects proofreading and exhibits a high degree of inaccurate DNA synthesis, but also induces chromosomal breakage, chromosomal aberrations, and aneuploidy." (PMID 37891003, 2024). "It was recently demonstrated that POLE mutations affecting only proofreading could predict anti–PD-1 efficacy in mismatch repair–proficient tumors revealing POLE proofreading deficiency as a new tissue-agnostic biomarker for cancer immunotherapy." (PMID 37891003, 2024). "The enhanced genomic damage and immune activation associated with POLE mutations suggest that cancers with POLE mutation may be more sensitive to immune checkpoint blockade therapy." (PMID 38238314, 2024). "We examined the potential relationship between the presence of histone mutations and mutations in POLE and found that the presence of POLE mutations in cancer patients is associated with the presence of histone mutations (Fischer’s exact test one-sided p-value < 0.001, odds ratio of 6.01)." (PMID 37444547, 2023). "The amino acid residues found mutated in POLE occur in the exonuclease domain and initial characterization of the mutant enzymes showed that, like catalytic active site mutations, the cancer mutations impaired exonuclease proofreading activity, though to varying degrees." (PMID 37388540, 2023). "From this data, it could be inferred that somatic POLE mutations are early events in the cancers in which they occur." (PMID 36672501, 2023). "Another article published in 2016, based on the analysis of the TCGA database, showed that cancers carrying POLE mutations were good candidates for immune checkpoint inhibitor therapy, which provided support for subsequent multiple immune checkpoint inhibitor studies." (PMID 37417594, 2023). "Molecular analysis revealed that the patient carried the PIK3CA H1047R cancer mutation and the POLE F699fs*11 mutation that is associated with high TMB and may benefit from immune checkpoint inhibition." (PMID 37187745, 2023). "Other studies have shown that germline alleles of POLE mutations lead to a cancer-prone phenotype." (PMID 37388540, 2023). "However, POLE T278K as a driven mutation in other type of cancers has been reported in two previous studies." (PMID 36765365, 2023). "Moreover, we found that both the two nonsense mutations in MSH6 were caused by a G > T transversion in AGA context, which was a representative characteristic of pathogenic POLE EDMs related cancers as confirmed in several previous studies." (PMID 36765365, 2023). "In humans, there are far fewer cancer driver mutations in POLD1 than in POLE." (PMID 37388540, 2023). "Moreover, germline or somatic mutations in the exonuclease domain of POLE were found to increase the mutation rate and risk of cancer development in the colon and endometrium." (PMID 35883600, 2022).
cancer (continued). "POLE mutations outside the exonuclease domain predicted to be deleterious are also observed in cancers, but it is unknown whether they are similarly associated with response to ICIs." (PMID 35274726, 2022). "In addition, other somatic point mutations in the polymerase domain of PolE (R567C, K593C, S595P, E611K, and L621F) and a deletion frameshift in the middle region of the PolE gene (V1446fs *3) are possible pathogenic factors in cancer." (PMID 35326618, 2022). "Non-canonical functions beyond DNA replication and proofreading have been previously proposed for Pol ε, but whether cancer-associated POLE mutations outside the exo-domain may impact such functions remains to be investigated." (PMID 35274726, 2022). "Deficiencies and mutations in PolE cause severe developmental abnormalities and cancers." (PMID 36402816, 2022). "Pathogenic POLE mutations outside the exonuclease domain may result in altered functions beyond DNA replication and proofreading which render cancers sensitive to ICIs." (PMID 35274726, 2022). "In addition, we identified POLE V1368M somatic mutations in other cancer types and germline mutations in 2 separate patients associated with familial colon cancer syndromes." (PMID 35274726, 2022). "MMR deficient or PolE-mutant tumors rapidly accumulate large amounts of mutations (~600 mutations/cell division), reaching but not exceeding, ~20,000 exon mutations in under six months, suggesting a threshold compatible with cancer cell survival." (PMID 35326618, 2022). "Even greater heterogeneity may arise in human cancers when more potent POLE mutator alleles occur in combination with MMR deficiency." (PMID 33398111, 2021). "Germline POLE/POLD1 mutations cause familial cancer predisposition." (PMID 34594041, 2021). "However, in some cancers, defective proofreading due to acquired POLE/POLD1 exonuclease domain mutations causes markedly elevated somatic mutation burdens with distinctive mutational signatures." (PMID 34594041, 2021). "Furthermore, the antitumor immune response is activated in cancer patients with POLE mutations who are benefited by immuno-oncology treatment." (PMID 34950188, 2021). "Moreover, many immune cell subsets, including B cells, T cells, dendritic cells, macrophages, and neutrophils, were significantly associated with POLE expression in cancers to varying degrees, particularly in ccRCC." (PMID 34950188, 2021). "In addition, human cancer cells are heterozygous for the POLE-P286R mutation, while the pol2-P287R mutation accumulation experiment used a haploid strain, so the mutagenic burden on mismatch repair would have been greater in the yeast strain." (PMID 34228709, 2021). "Here, we describe the genome-wide mutation profiles of distinct POLE mutant cancers." (PMID 32012149, 2020). "The second contained cancers with mutated POLE but intact MMR." (PMID 32170069, 2020). "Immunotherapy provided very encouraging data on survival for MSI-H/dMMR mCRC and might be the best area of research, even for MSS POLE-1 or POLD1 mutant cancers, due to their high mutational burden." (PMID 32413973, 2020). "Importantly, we showed that perturbation of POPS’s functions increases genome rearrangements, thus shedding light on potential genomic consequences of human POLE POPS variants present in cancers." (PMID 32415104, 2020). "Since we had identified that different POLE mutants have different mutation spectra, were interested to determine whether this may predispose cells to specific additional cancer driver mutations." (PMID 32012149, 2020). "These 15 cancer types contained 138 cases with POLE mutations anywhere in the exome." (PMID 32838755, 2020). "Thus, elevated ERVs associated with high POLE expression have other effects resulting in inhibited cancer growth." (PMID 32433714, 2020). "Somatic mutations in POLE have also been reported in these cancers." (PMID 31864301, 2019).
cancer (continued). "Mutations in polymerase ε (POLE) confer favorable prognosis and outcomes in various cancer types, but their role in non-small cell lung cancer (NSCLC) is unknown." (PMID 29650000, 2018). "Interestingly, cancers only developed in mice homozygous for proofreading deficient polD1 and polE alleles and in mismatch proficient background." (PMID 29500597, 2018). "In the mice model, when the exonuclease domain of Pol δ (encoded by the POLD1 gene) or Pol ɛ (encoded by the POLE gene) was inactivated by mutation at exonuclease, catalytic residue elevated base substitution mutation rates, and increased incidence of cancers was observed." (PMID 29500597, 2018). "Additionally, the number of POLD1 and POLE mutations in human cancers will likely increase substantially as more cancer genomes are sequenced." (PMID 28117753, 2017). "The acquisition of the POLE mutation leading to hypermutation can accelerate cancer development." (PMID 27612425, 2016). "Single cell resolution replication studies of human POLE mutant cells are needed to test the hypothesis of mutator volatility in cancer." (PMID 25868109, 2015). "An important question regarding these cases is whether special properties of the cancer itself (e.g., specific POLE mutations, a particular genomic or epigenetic context) or patient-related attributes (e.g., host’s immune competence), are responsible for the unfavorable disease dissemination." (PMID 40958870, 2025). "The last decade has witnessed the identification in cancers from many tissue types of multiple somatically acquired missense mutations clustering in the sequence encoding the exonuclease proofreading domain of POLE with a high incidence in colorectal (3%) and endometrial (8%) cancers." (PMID 37891003, 2024). "In addition, evidence from studies on human cancers and cancer cell lines carrying different POLE mutations suggests that there may be some differences in the mutational signatures of P286R and V411L in vivo." (PMID 37592814, 2023). "CRC and EC cancer patients with somatic POLE ED mutations have been shown to have a favourable prognosis and it would be interesting in future studies to investigate whether the prognosis of cancer patients with germline POLE or POLD1 mutations is also better." (PMID 33948826, 2022). "In addition, our analysis of a cohort of ICI-treated patients indicates that a subset of POLE mutations outside of the exo-domain may predict ICI benefit among cancers with low or intermediate TMB." (PMID 35274726, 2022). "Thus mammalian cells heterozygous for the POLE-P286R mutation may be ideally predisposed for cancer formation, having a sufficiently high mutation rate but without defects in cell cycle progression." (PMID 34228709, 2021). "Mutations in POLE, which could lead to the hypermutated and ultramutator phenotypes and possibly improved response to immune therapies in patients, were observed subclonal in both cancers." (PMID 33980813, 2021). "A recent study also suggested that cells with the V411L mutation may, in fact, take a shorter path to cancer: a germline V411L variant was identified in a pediatric CRC case with an onset at least 10 yr earlier than is typical for carriers of other POLE mutations." (PMID 29352080, 2018). "Therefore it appears that POLE defects may cause characteristic driver lesions in these cancer types." (PMID 29748584, 2018). "Furthermore, we show that early somatic POLE mutations are likely to cause an enrichment of clonal neoantigens that may explain the goodprognosis of cancers carrrying these variants, and their excellent response to immune checkpoint inhibitors." (PMID 29604063, 2018). "Therefore, solely focusing upon POLE and/or EDMs may fail to identify all the replicative polymerase variants that contribute to cancer etiology." (PMID 28117753, 2017).
cancer (continued). "In addition, POLE has been linked to an early onset cancer case raising the question whether this specific POLE mutation may confer a more severe phenotype than previously reported POLE/POLD1 mutations." (PMID 28331556, 2017). "Similarly, analysis of the burden of deleterious mutations accumulated in POLE proofreading-mutant cancers may provide insights into their behavior." (PMID 25505230, 2015). "This POLE-specific global suppression differs from the broader EC pattern observed in the cancer-versus-healthy comparison, where prominent oncomiR up-regulation (miR-200 family, miR-181a, miR-20b) occurred alongside let-7 loss." (PMID 41226475, 2025). "In this report, we re-analyzed cancer genomes deposited in COSMIC or cBioPortal to identify driver mutations in other genes that co-occur with POLe mutations." (PMID 40806338, 2025). "Independently from the ClinGen panel, recommendations for the classification of POLE and POLD1 variants in the context of cancer predisposition have also been published." (PMID 40237887, 2025). "PolED also helps interpret germline POLE and POLD1 variants to facilitate risk assessment and surveillance of families with cancer predisposition syndromes." (PMID 41263451, 2025). "Another study in 2022 retrieved the data of 458 patients with cancer with POLE mutations from NGS reports of 14,229 patients with various cancer types, with 15% of POLE mutations identified as pathogenic." (PMID 40310397, 2025). "Further analyses of these sets of neomers show that they can be used not only to classify cancer tissue of origin, but also to identify additional cancer features, such as MSI or POLE deficiency, with high accuracy." (PMID 40841759, 2025). "For example, the mere 2-3-fold increase in mutation rates increases the cancer risk of patients with MUTYH, and 1.2-7-fold for POLE and POLD1 mutations." (PMID 40243939, 2025). "In cancers with relatively high CMTR2 mutation frequencies, the mutations were often associated with hypermutated subtypes characterized by POLE mutations or microsatellite instability-high (MSI-H)." (PMID 41198678, 2025). "Next generation sequencing was performed and revealed a pathogenic POLE-EDM (p.A456P) and multiple pathologic mutations in other known cancer associated genes." (PMID 40958870, 2025). "The discovery of a multitude of POLE/POLD1 mutations in human cancers in the 2010s further boosted functional analysis efforts, which now specifically focused on cancer-associated variants with suspected clinical significance." (PMID 41263451, 2025). "In silico analysis has proved that POLE mutant cancers display more antigenic neoepitopes than other ECs, providing a potential rational for POLE immunogenicity." (PMID 39239272, 2024). "These cancers are often linked to constitutional MMRD and the subsequent acquisition of a somatic POLE/POLD1 mutation, which results in the rapid accumulation of mutations." (PMID 39204096, 2024). "Our case adds to the growing literature showing POLE-mutant cancers responding to checkpoint inhibition." (PMID 37239414, 2023). "Given that these cancers are relatively common and appear to respond to checkpoint inhibition, consideration should be given to checking MSS EOCRC for somatic POLE mutations." (PMID 36672501, 2023). "Germline mutations in the exonuclease domain of Pol ε (POLE) and δ (POLD1) predispose to colorectal cancer (CRC) and other types of cancer." (PMID 36765365, 2023). "The risk score was associated with molecular subtypes (p < 0.01), cancer status (p < 0.01) and age (p = 0.03), in EEA patients, POLE hypermutation and MSI subtypes have low risk values, while high CNV is associated with high-risk values." (PMID 38085674, 2023).
cancer (continued). "They found that the T cell infiltrate in POLE mutant cancers was the same as the infiltrate in the precursor lesions, and the absolute number of neoantigens was much higher than in other cancers." (PMID 36672501, 2023). "Carcinomas that are genomically characterized by CNH, CNL, MSI, and POLE mutations are recognized as distinct categories within EC and are associated with varying clinical outcomes." (PMID 38234757, 2023). "People with germline mutations in POLE/POLD or DNA mismatch repair genes accumulate mutations at a faster rate, which would disproportionately increase cancer risk in cancer types with a higher number of driver mutations." (PMID 36000228, 2022). "By sequencing analysis, we confirmed that these two MSI‐H cancer tissues had mutations in genes related to DNA repair, included MLH1 and POLE, in both the original tissue and cultured organoids." (PMID 34850547, 2022). "Biallelic mutations reveal ultraviolet light damage hotspots at E26 transformation-specific (ETS) and nuclear factor of activated T cells (NFAT) binding sites, and hypermutable motifs in POLE-mutant and other cancers." (PMID 35145300, 2022). "There are two previously published cases of childhood/AYA cancer caused by digenic inheritance of a heterozygous PMS2 PV and a heterozygous POLE exonuclease PV." (PMID 36291559, 2022). "Patients with luminal cancers and a high TMB displayed a higher prevalence of mutations in MSI-related genes and genes encoding for the proofreading polymerases epsilon, POLE and delta, POLD1 compared with the group with low TMB." (PMID 35329928, 2022). "The first reported immunotherapy in PolE-mutant cancer was carried out in non–small cell lung cancer (NSCLC)." (PMID 35326618, 2022). "Analyses of mutation burdens in non‐cancer genomes from PPAP provide a first in vivo measurement of POLD and POLE proofreading activity in human tissues and its importance in protecting from cancer transformation in selected tissues." (PMID 35435316, 2022). "Compared with BRAF mutant/PIK3CA wild type cancers, double mutant cancers were even more often MSI or POLE positive." (PMID 36079062, 2022). "In 2019, Wang and his colleagues, through analyzing medical data of 47,721 patients with various cancer types with POLE/POLD1 mutations, proposed that POLE/POLD1 mutations are promising potential predictive biomarkers for positive ICI outcomes." (PMID 36483562, 2022). "In fact, these individuals experience multiple, early‐onset cancer occurrences during life, thereby the inherited disease caused by the loss of POLD and POLE proofreading activity has been termed polymerase proofreading‐associated polyposis (PPAP)." (PMID 35435316, 2022). "summarized the POLE/POLD1 mutation rate in 47,721 patients with different cancer types and identified that patients harboring POLE/POLD1 mutations have a significantly higher TMB." (PMID 34026601, 2021). "The effects of POLE expression on the progression and prognosis of cancers provide a target for drug therapy, to achieve individualized precise treatment." (PMID 34950188, 2021). "POLE/POLD1 mutations remained an independent risk factor for greater response to immune checkpoint inhibitor after adjusting for MSI status and cancer type." (PMID 33916348, 2021). "The POLD1 gene has been found silenced in several cancer types—mostly, in conjunction with a defective POLE gene—with increased genome instability and DNA damage effects." (PMID 34026645, 2021). "They used a cohort of 92,438 tumors obtained from over 100 different cancer types and showed that the mutation of MMR genes or POLE gene would result in higher TMB in a pan-cancer scenario." (PMID 34198473, 2021).